CARM1 (coactivator associated arginine methyltransferase 1)
Diseases named in the same sentence as CARM1 in open-access papers (continued):
Sharing a sentence is not in itself a finding about the gene and the disease.
Hodgkins lymphoma (3 papers, 2012 to 2023). A heterogeneous group of malignant lymphoid neoplasms of B-cell origin characterized histologically by the presence of Hodgkin and Reed-Sternberg (HRS) cells in the vast majority of cases. "CARM1 protein levels were reported to be higher in Hodgkin lymphoma cell lines than human germinal center (GC) B cells, and high CARM1 levels were detected in Reed-Sternberg cells in Hodgkin patient samples." (PMID 37536629, 2023). "We first show that the protein arginine methyltransferases, CARM1, PRMT1 and PRMT5 are strongly expressed in Hodgkin Reed-Sternberg (HRS) cells, and up-regulated in Hodgkin's lymphoma (HL) cell lines." (PMID 25436604, 2012).
oral cancer (3 papers, 2019 to 2025). "As our results clearly suggest that YY1 positively regulates CARM1 promoter and CARM1 is highly overexpressed in oral cancer patient samples, we wanted to find out whether CARM1 overexpression is caused by upregulation of YY1 in the context of oral cancer." (PMID 31217904, 2019). "Behera's research identified that in oral cancer, CARM1 exhibits abnormally high expression levels and demonstrates carcinogenic functions." (PMID 39964832, 2025). "Keeping in mind the need of the hour, we put our effort in the present study to elucidate the molecular function of CARM1, a prospective oncogenic candidate and a probable therapeutic target in the context of oral cancer." (PMID 31217904, 2019). "We wanted to further investigate the driving force behind transcriptional upregulation of CARM1 in oral cancer." (PMID 31217904, 2019). "In the present study we uncover an oncogenic function of CARM1 in the context of oral cancer, where it was found to be overexpressed." (PMID 31217904, 2019). "The genome wide transcription factor enrichment profile from ENCODE repository revealed a few prospective TF candidates for regulation of CARM1 expression in oral cancer such as E2F4, CTCF, YY1 and cMyc etc.." (PMID 31217904, 2019). "We also observed a positive correlation in protein expression of both YY1 and CARM1 in oral cancer tumor tissues." (PMID 31217904, 2019). "Taken together, these data prove that YY1 positively regulates CARM1 expression and is at least partly responsible for the overexpression of CARM1 in oral cancer patient tumors." (PMID 31217904, 2019). "This would help us to distinguish the set of YY1 responsive genes which are CARM1 dependent in the context of oral cancer." (PMID 31217904, 2019). "Clinically relevant RNAi therapy and small molecule inhibitors could also be developed and employed targeting YY1 and CARM1 to suppress oral cancer growth in near future." (PMID 31217904, 2019). "We were interested to investigate the expression status of CARM1 in oral cancer patient samples." (PMID 31217904, 2019). "In the present study CARM1 was also found to be upregulated in oral cancer patient tumor tissues." (PMID 31217904, 2019). "The study also revealed that YY1 acts as a positive regulator of the CARM1 gene promoter, and silencing YY1 in oral cancer cells significantly reduces CARM1 expression." (PMID 39964832, 2025). "Taken together, CARM1 and YY1 were found to regulate each other in a positive feedback loop to facilitate oral cancer progression." (PMID 31217904, 2019). "Transcriptomic analysis with knock down of CARM1 in the context of oral cancer would be necessary to identify the genes which are regulated by both YY1 and CARM1." (PMID 31217904, 2019). "In the present study investigation with silencing of both CARM1 and YY1 unraveled the oncogenic functions of both the proteins towards oral cancer manifestation." (PMID 31217904, 2019). "The inducible knock-down of YY1 in AW8507_Tet-ON-shYY1 cells with Doxycycline treatment was found to lead to reduction in expression of CARM1, indicating transcriptional regulation by YY1 in the context of oral cancer." (PMID 31217904, 2019). "Therefore, a positive feedback loop is formed between CARM1 and YY1, mutually regulating each other, thereby driving the progression of oral cancer." (PMID 39964832, 2025). "Inducible knock-down of CARM1 did not affect the proliferation ability of oral cancer cells; however it inhibited migration potential and colony formation by oral cancer cells." (PMID 31217904, 2019). "We also identify YY1 to be a positive regulator of CARM1 gene promoter, where silencing of YY1 in oral cancer cell line could lead to reduction in expression of CARM1." (PMID 31217904, 2019).
osteoporosis (3 papers, 2020 to 2023). A condition of reduced bone mass, with decreased cortical thickness and a decrease in the number and size of the trabeculae of cancellous bone (but normal chemical composition), resulting in increased fracture incidence. "In vivo experiments revealed that CARM1 significantly decreased bone loss in osteoporosis model mice." (PMID 37649137, 2023). "In brief, the results indicated that CARM1 supplementation can reduce bone loss and stimulate bone formation to a certain extent in osteoporosis model mice." (PMID 37649137, 2023). "The results of animal experiments suggest that CARM1 can significantly reduce bone loss in osteoporosis model mice." (PMID 37649137, 2023). "To clarify the coordinated character of CARM1 in bone resorption and bone formation, we first searched and analysed the data related to osteoporosis and osteogenic and osteoclastic differentiation in the GEO database." (PMID 37649137, 2023). "We used RT‐PCR to detect CARM1 expression in bone samples from patients with osteoporosis, and CARM1 expression was down‐regulated in the osteoporosis group compared with the control group." (PMID 37649137, 2023). "The results of calcein double labelling experiment confirmed that CARM1 promoted bone formation in osteoporosis model mice in vivo, and the mineral apposition rate (MAR) and bone formation rate (BFR) of mouse bone samples in Carm1‐OE group were higher than those in control group." (PMID 37649137, 2023). "Our data suggest that CARM1 coordinates osteogenic and osteoclastic differentiation by regulating metabolism, and CARM1 may be a new therapeutic target for osteoporosis in the future." (PMID 37649137, 2023). "The PFK activity test showed that PFK activity decreased in bone samples from patients with osteoporosis, and in mc3t1‐e1 and RAW264.7 cells, the regulation of PFK activity by CARM1 could be reversed by MK2206 (an AKT inhibitor) and Compound C (an AMPK inhibitor), respectively." (PMID 37649137, 2023).
rhabdomyosarcoma (3 papers, 2021 to 2022). A rare aggressive malignant mesenchymal neoplasm arising from skeletal muscle. "The expression of PRMT1, CARM1, PRMT5, PRMT7, PRMT8 and PRMT9 were all elevated in rhabdomyosarcoma, CARM1 and its direct interaction with histone acetyltransferase PCAF jointly were also detected to exert an increased expression of myogenin gene and lead to rhabdomyosarcoma cell differentiation." (PMID 35311114, 2022).
Atrophy (2 papers, 2023 to 2025). Any weakening or degeneration, especially through lack of use. "In protein metabolism, CARM1 plays a role in the onset and progression of muscle atrophy by regulating the ubiquitin-proteasome system and nonsense-mediated mRNA decay." (PMID 41488004, 2025). "We then studied, during neurogenic atrophy, the effect of CARM1 inhibition on PGC-1α expression, a potent regulator of mitochondrial biogenesis in skeletal muscle." (PMID 37493245, 2023). "The purpose of the present study was to further investigate the role of CARM1 in the maintenance and plasticity of skeletal muscle mass and function at rest and during neurogenic muscle atrophy." (PMID 37493245, 2023). "Conversely, in fasting-induced atrophy models, the methyltransferase activity of CARM1 decreased in both mice and humans, while protein levels remained unchanged—a stark contrast indicating potentially distinct regulatory mechanisms for CARM1 across different atrophy patterns." (PMID 41488004, 2025).
bladder cancer (2 papers, 2022 to 2024). "For bladder cancer, LA inhibited arginine methyltransferase (PRMT) activity in bladder cancer by targeting CARM1, thereby downregulating the expression of an epigenetic modification enzyme." (PMID 35677438, 2022).
cervical cancer (2 papers, 2022 to 2025). A primary or metastatic malignant neoplasm involving the cervix. "On another note, Co-activator-associated arginine methyltransferase 1 (CARM1/PRMT4) methylates arginine residue R217 in macrophages, human cervical cancer cells, and human embryonic stem cells, enhancing HuR’s stabilization of target gene mRNAs." (PMID 41200195, 2025). "It is demonstrated that CARM1 is highly expressed in cervical cancer tissues and radio-resistant cervical cancer cells, while miR-16-5p expression is low." (PMID 35967381, 2022). "Under irradiation, up-regulation of CARM1 can induce radiotherapy resistance of cervical cancer cells, while overexpression of miR-16-5p or CARM1 knockdown could inhibit the survival of CC cell and induced apoptosis." (PMID 35967381, 2022).
chronic kidney disease (2 papers, 2020 to 2024). Impairment of the renal function secondary to chronic kidney damage persisting for three or more months. "Calycosin suppresses autophagy and oxidative stress in chronic kidney disease skeletal muscle atrophy by regulating the AMPK/SKP2/CARM1 signaling pathway." (PMID 38650035, 2024).
Duchenne muscular dystrophy (2 papers, 2022 to 2025). Duchenne muscular dystrophy (DMD) is a neuromuscular disease characterized by rapidly progressive muscle weakness and wasting due to degeneration of skeletal, smooth and cardiac muscle. "It is possible that one of the consequences of CARM1 misregulation through its hyperphosphorylation and sequestration in Duchenne muscular dystrophy is an impairment in the autophagy pathways." (PMID 36103286, 2022). "In addition to Duchenne muscular dystrophy, CARM1 is potentially involved in muscle ageing through its contributions to autophagy." (PMID 36103286, 2022). "In Duchenne muscular dystrophy (DMD) models, the inhibition of CARM1 activity reduces satellite cell asymmetric division and impairs muscle regenerative capacity." (PMID 41488004, 2025). "Furthermore, given the extent to which CARM1 is misregulated in mdx satellite cells, it is also likely that pre-mRNA alternative splicing is misregulated and has a role in disease progression and the regenerative deficit observed in Duchenne muscular dystrophy." (PMID 36103286, 2022).
muscle atrophy (2 papers, 2023 to 2025). The loss of muscle tissue due to inactivity or disease. "Research indicates that skeletal muscle atrophy is primarily associated with abnormal activation of the ubiquitin-proteasome system, with CARM1 playing a crucial regulatory role in this process." (PMID 41488004, 2025). "We sought to explore the impact of pharmacological CARM1 inhibition on denervation-induced muscle atrophy." (PMID 37493245, 2023). "This suggests that dysregulated CARM1 expression correlates with muscle diseases, and targeting CARM1 may offer a novel therapeutic strategy for muscle atrophy." (PMID 41488004, 2025). "Recent studies have investigated CARM1 during conditions of neurogenic skeletal muscle atrophy." (PMID 37493245, 2023). "Thus, further research is needed to understand the role of CARM1 in human muscle atrophy." (PMID 37493245, 2023).
muscular atrophy (2 papers, 2020 to 2025). "A recent study showed that CARM1 played a role in muscular atrophy." (PMID 32910538, 2020). "Furthermore, our study showed that CARM1 may be a crucial regulator of skeletal muscle atrophy and suggested that calycosin may be a potential therapy for skeletal muscle atrophy induced by CKD, malnutrition or other conditions." (PMID 32910538, 2020).
Obesity (2 papers, 2020 to 2024). Accumulation of substantial excess body fat. "This is the first time that normal genetic variation in these genes has been related to bone mass, and moreover, of great potential interest in cardiovascular risk assessment, the first time that genetic variants in CARM1 gene have been correlated with obesity and fasting insulin levels." (PMID 33004909, 2020). "In conclusion, SNPs of the DNMT3A and CARM1 genes are associated with BMD, in the latter case probably owing to a strong correlation with obesity and fasting insulin levels." (PMID 33004909, 2020).
psoriasis (2 papers, 2019 to 2024). An autoimmune condition characterized by red, well-delineated plaques with silvery scales that are usually on the extensor surfaces and scalp. "Rs892085 is located in an intron of the QTRT1 gene, in close proximity to the ILF3 and CARM1 genes, and has been associated with psoriasis, with the risk allele A." (PMID 38898675, 2024).
serous ovarian carcinomas (2 papers, 2018 to 2025). "Karakashev's research group found that patients with high‐grade serous ovarian cancer (HGSOC) exhibiting high CARM1 expression have a poorer prognosis and limited treatment options." (PMID 39964832, 2025). "Fukumoto, Magno, and Zhang team noted in their review that in high‐grade serous ovarian cancer (HGSOC), the SWI/SNF complex is regulated by CARM1." (PMID 39964832, 2025). "We cross-referenced the list of 218 direct EZH2/H3K27Me3 target genes with 528 TCGA high-grade serous ovarian carcinomas gene expression profiles and identified genes that negatively correlated with CARM1 expression in these cases." (PMID 29434212, 2018).
spinal muscular atrophy (2 papers, 2021 to 2025). A motor neuron disease that affect the muscles, and characterized by muscle weakness and atrophy resulting from progressive degeneration and irreversible loss of the anterior horn cells in the spinal cord (i.e., lower motor neurons) and the brain stem nuclei. "The CARM1/PRMT4 relationship with the survival motor neuron (SMN) gene, which, when mutated, promotes spinal muscular atrophy (SMA), has been thoroughly studied." (PMID 33440687, 2021). "In spinal muscular atrophy (SMA) models, CARM1 protein levels are significantly elevated in spinal motor neurons and muscle tissues." (PMID 41488004, 2025).
squamous cell carcinoma (2 papers, 2022 to 2024). A carcinoma arising from squamous epithelial cells. "For instance, circHMGB2 drives immunosuppression and anti-PD-1 resistance in NSCLC and squamous cell carcinomas via the miR-181a-5p/CARM1 axis." (PMID 38082189, 2024).
acute coronary syndrome (1 paper, 2022). Signs and symptoms related to acute ischemia of the myocardium secondary to coronary artery disease. "CARM1 is essential for the activation of a subset of NF-κB-dependent genes that encode chemokines, triggering plaque vulnerability, and unstable atherosclerotic plaques that lead to the onset of the acute coronary syndrome (ACS)." (PMID 35757636, 2022).
adrenocortical carcinoma (1 paper, 2022). "It is worth noting that all cases of uterine carcinosarcoma (~ 7%), adrenocortical carcinoma (~ 3.5%) and mesothelioma (> 2%) with gene variation have “amplification” mutation type, while all cases of DLBCL (> 4%) have copy number deletion of CARM1." (PMID 35033016, 2022).
Benign Breast Tumors (1 paper, 2015). "We used recently developed antibodies to detect differential CARM1 isoform expression in subcellular compartments and among malignant and benign breast tumors." (PMID 26030442, 2015).
cardiac hypertrophy (1 paper, 2025). "Interestingly, this study demonstrates a previously unannotated functional link between STAT3 and CARM1 in the pathogenesis of pathological myocardial hypertrophy." (PMID 40192103, 2025). "We hypothesized that USP20‐STAT3 axis ameliorates cardiac hypertrophy through transcriptional regulation of Carm1." (PMID 40192103, 2025). "Our findings reveal a novel cardiomyocyte‐specific USP20‐STAT3‐CARM1 (coactivator‐associated arginine methyltransferase 1) axis that regulates cardiac hypertrophy and heart failure, and position USP20 as a potential therapeutic target for pathological cardiac hypertrophy and heart failure." (PMID 40192103, 2025).
cervical squamous cell carcinoma (1 paper, 2022). A squamous cell carcinoma arising from the cervical epithelium. "Compared with the cases with CARM1 change, Cervical squamous cell carcinoma and endocervical adenocarcinoma (CESC) cases without altered CARM1 show better prognosis in PFS (P = 0.0239) and DFS (P = 2.892e-5), but not OS (P = 0.883) and DSS (P = 0.870)." (PMID 35033016, 2022).
chordoma (1 paper, 2025). Chordomas are rare malignant tumors arising from embryonic remnants of the notochord in axial skeleton. "Significant enrichments were identified in dedifferentiated chordoma, specifically for CARM1 (100%, p < 10−10), PRKN (66.67%, p < 10−10), and MTAP (100%, p = 0.009), suggesting these mutations may uniquely characterize dedifferentiated chordoma." (PMID 39941902, 2025).
chronic obstructive pulmonary disease (1 paper, 2023). A chronic and progressive lung disorder characterized by the loss of elasticity of the bronchial tree and the air sacs, destruction of the air sacs wall, thickening of the bronchial wall, and mucous accumulation in the bronchial tree. "Furthermore, Carm1+/− heterozygotes are susceptible to chronic obstructive pulmonary disease when challenged with cigarette smoke, implicating CARM1 in airway epithelial regeneration and repair." (PMID 37536629, 2023).
colorectal tumors (1 paper, 2010). "Out of the 65 colorectal tumors, 49 expressed high levels of CARM1 (a score of 2-3), accounting for 75% of the total specimen." (PMID 20462455, 2010). "Follow-up studies with surgical specimens further demonstrated that CARM1 was commonly expressed in over 75% of colorectal tumors (49 out of 65 tumors expressed high levels of CARM1)." (PMID 20462455, 2010). "Surprisingly, 68% of colorectal tumors overexpressed CARM1; however, overexpression was very limited in all other tumors." (PMID 20462455, 2010). "Overexpression of CARM1 in the colorectal tumors was statistically significant (student t-test p < 0.001), confirming the CARM1 overexpression identified on the tumor tissue microarray." (PMID 20462455, 2010). "Our study, however, demonstrated that CARM1 was mainly overexpressed in colorectal tumors; with a frequency as high as 68%, compared to other tumors from the brain, skin, ovary, lymphocytes, lung, breast, and prostate." (PMID 20462455, 2010).
COVID-19 (1 paper, 2025). A disease caused by infection with severe acute respiratory syndrome coronavirus 2. "rs73009538 in the CARM1 region associated with type I interferon, and the deficiency of type I IFN response is one of the key factors in severe COVID-19." (PMID 40034745, 2025).
endothelial dysfunction (1 paper, 2025). In vascular diseases, endothelial dysfunction is a systemic pathological state of the endothelium (the inner lining of blood vessels) and can be broadly defined as an imbalance between vasodilating and vasoconstricting substances produced by (or acting on) the endothelium. "We also identified potential target genes, including those involved in inflammation signaling (CARM1), endothelial dysfunction (INTS12), and antiviral immune response (RAVER1), which may require further investigation." (PMID 40034745, 2025).
familial cancers (1 paper, 2021).